CNIH3 (cornichon family AMPA receptor auxiliary protein 3)
Description:
Regulates the trafficking and gating properties of AMPA-selective glutamate receptors (AMPARs). Promotes their targeting to the cell membrane and synapses and modulates their gating properties by regulating their rates of activation, deactivation and desensitization.
Synonyms: CNIH-3; FLJ38993
Tractability: Antibody: UniProt places it where antibodies can reach, with medium confidence; UniProt predicts a signal peptide or a membrane-spanning region; its Gene Ontology location is reachable by antibodies, with medium confidence. PROTAC: its protein half-life has been measured.
Safety:
Unwanted effects reported when the protein is acted on. In parentheses: how it was acted on, where the effect was seen, and who reports it.
opioid dependence (source: ClinPGx)
Gene: Protein-coding gene on chromosome 1 (224,434,660 to 224,740,559, forward strand). Ensembl gene ENSG00000143786.
Subcellular location: Postsynaptic cell membrane
Pathways (Reactome):
Vesicle-mediated transport: COPII-mediated vesicle transport; Cargo concentration in the ER
Gene Ontology:
Molecular function: protein binding; signaling receptor binding; channel regulator activity
Biological process: regulation of AMPA receptor activity; synaptic transmission, glutamatergic; neurotransmitter receptor localization to postsynaptic specialization membrane; vesicle-mediated transport
Cellular component: AMPA glutamate receptor complex; dendrite; dendritic shaft; endoplasmic reticulum membrane; endoplasmic reticulum-Golgi intermediate compartment membrane; ER to Golgi transport vesicle membrane; postsynaptic membrane; synapse; glutamatergic synapse
Genetic constraint (gnomAD): Loss-of-function variants: 11 observed, 18.5 expected, observed/expected ratio (o/e) 0.59, 90% interval 0.37 to 0.98. The upper end of that interval is the gene's LOEUF score, 0.98, which puts it in group 4 of 6, group 1 being the genes least tolerant of losing a copy. Missense variants: 131 observed, 158.3 expected, observed/expected ratio (o/e) 0.83, 90% interval 0.72 to 0.96. Synonymous variants: 47 observed, 58.35 expected, observed/expected ratio (o/e) 0.81, 90% interval 0.64 to 1.03.
Homologues: Orthologues: chimpanzee CNIH3 (100% identical), mouse Cnih3 (100% identical), rabbit CNIH3 (100% identical), rat Cnih3 (99% identical), dog CNIH3 (99% identical), macaque CNIH3 (97% identical), tropical clawed frog cnih3 (92% identical), zebrafish cnih3 (81% identical), guinea pig CNIH3 (77% identical), pig CNIH3 (73% identical), Drosophila melanogaster cni (48% identical), Caenorhabditis elegans cni-1 (46% identical). Paralogues in human: CNIH2 (81% identical), CNIH1 (68% identical), CNIH4 (28% identical), PPCS (22% identical).
Diseases named in the same sentence as CNIH3 in open-access papers:
CNIH3 is named in the same sentence as 10 diseases in open-access papers, as found by Europe PMC text mining. Sharing a sentence is not in itself a finding about the gene and the disease. The quoted sentences say what the papers report.
opioid dependence (3 papers, 2020 to 2023). "Cnih3 was of interest because human genetic association studies suggest polymorphism in this region may be protective against opioid dependence, a disease that involves hijacking of normal reward mechanisms including learning and memory (i.e., dorsal hippocampal) processes." (PMID 36849260, 2023).
breast carcinoma (1 paper, 2022). "The novel 5-hmC candidates such as TXNL1, and CNIH3 implicate a pro-oncogenic role in breast cancer." (PMID 36230901, 2022). "Our validation analysis confirmed that the gain of 5-hmC in TXNL1, BNIPL, CNIH3 and loss of 5-hmC in CHODL, ZBTB16, SP8, and HIC2 in breast cancer samples." (PMID 36230901, 2022). "Novel 5-hmC candidates such as TXNL1, CNIH3, BNIPL, and CHODL were found to be promising diagnostic and therapeutic markers for breast cancer." (PMID 36230901, 2022).
Dystonia (1 paper, 2022). An abnormally increased muscular tone that causes fixed abnormal postures. "The endoplasmic reticulum localization of CNIH3 and its interplay with lipids in complex with AMPA receptors suggests that it could be one link between torsinA function and the synaptic plasticity differences observed in animal models and in people with dystonia." (PMID 36874764, 2022).
cancer (1 paper, 2017). A tumor composed of atypical neoplastic, often pleomorphic cells that invade other tissues. "The locus on chromosome 1 holds the gene CNIH3, not known to be involved in any type of cancer, and the locus on chromosome 11 harbors the non-coding RNA gene RP11-266A24.1." (PMID 29299148, 2017).
CNIH3 also shares sentences with these, for which no sentence is quoted: schizophrenia (2 papers); alcohol dependence (1); Alzheimer disease (1); liposarcoma (1); opioid use disorder (1); sarcoma (1).